CNTF (ciliary neurotrophic factor)
Description:
Functions as a cytokine through the ciliary neurotrophic factor receptor (CNTFR) complex. The CNTFR complex indeed consists of the membrane-anchored non-signaling receptor CNTFR and the two signaling receptor subunits IL6ST/gp130 and LIFR that transduce the signal into the cell. Functionally, promotes neuronal survival, supports differentiation of various neuronal and non-neuronal cells, and importantly regulates oligodendrocyte progenitor proliferation. Mechanistically, ligand binding to the CNTFR induces dimerization of the IL6ST/gp130 and LIFR, which activates JAK tyrosine kinases (JAK1 or JAK2 and to lesser extent TYK2) bound to their intracellular domains. These kinases subsequently phosphorylate IL6ST/gp130 and LIFR. The tyrosine phosphorylated signaling receptors serve in turn as docking sites for recruitment and activation of signal transducer and activators of transcription (STAT3 and to lesser extent STAT1). Can also signal via trans-signaling using soluble forms of CNTFR. Seems to prevent the degeneration of motor axons after axotomy (By similarity).
Synonyms: HCNTF
Tractability: Small molecule: it has a binding pocket of medium quality. Antibody: its Gene Ontology location is reachable by antibodies, with high confidence.
Gene: Protein-coding gene on chromosome 11 (58,622,665 to 58,625,733, forward strand). Ensembl gene ENSG00000242689.
Subcellular location: Cytoplasm; Secreted
Subcellular location (Human Protein Atlas): Vesicles
Pathways (Reactome):
Immune System: IL-6-type cytokine receptor ligand interactions
Gene Ontology:
Molecular function: cytokine activity; growth factor activity; interleukin-6 receptor binding; protein binding; protein-containing complex binding; ciliary neurotrophic factor receptor binding
Biological process: cell surface receptor signaling pathway via STAT; ciliary neurotrophic factor-mediated signaling pathway; negative regulation of neuron apoptotic process; negative regulation of oligodendrocyte progenitor proliferation; positive regulation of gene expression; positive regulation of tyrosine phosphorylation of STAT protein; astrocyte activation; cell surface receptor signaling pathway via JAK-STAT; positive regulation of axon regeneration; signal transduction; regulation of programmed cell death
Cellular component: extracellular region; protein-containing complex; axon; glial cell projection; neuronal cell body; cytoplasm
Genetic constraint (gnomAD): Loss-of-function variants: 15 observed, 14.78 expected, observed/expected ratio (o/e) 1.02, 90% interval 0.68 to 1.55. The upper end of that interval is the gene's LOEUF score, 1.55, which puts it in group 6 of 6, group 1 being the genes least tolerant of losing a copy. Missense variants: 282 observed, 264.08 expected, observed/expected ratio (o/e) 1.07, 90% interval 0.97 to 1.18. Synonymous variants: 98 observed, 97.65 expected, observed/expected ratio (o/e) 1, 90% interval 0.85 to 1.19.
Homologues: Orthologues: chimpanzee CNTF (99% identical), rabbit CNTF (86% identical), rat Cntf (84% identical), pig CNTF (82% identical), mouse Cntf (82% identical), guinea pig CNTF (74% identical), zebrafish m17 (20% identical).
Diseases named in the same sentence as CNTF in open-access papers:
CNTF is named in the same sentence as 121 diseases in open-access papers, as found by Europe PMC text mining. Sharing a sentence is not in itself a finding about the gene and the disease. The quoted sentences say what the papers report.
retinal degeneration (40 papers, 2007 to 2025). Degeneration of the retina. "CNTF is a potent treatment in retinal degeneration pathologies, such as retinitis pigmentosa, underlying a possible interaction between CNTF and ApoE containing lipoproteins in the retina." (PMID 29507344, 2018). "Direct intraocular injection of CNTF has been shown to retard photoreceptor death caused by inherited forms of retinal degeneration or by light induced retinal damage." (PMID 20169166, 2010). "In addition, CNTF can rescue retinal degeneration due to various causes, including mutations in genes expressed by photoreceptors or the retinal pigment epithelium (RPE), as well as those induced by strong light or neurotoxins." (PMID 29795129, 2018). "Ciliary neurotrophic factor (CNTF) has been shown to be a potent neuroprotective cytokine in various animal models of retinal degeneration." (PMID 40671803, 2025). "The neurocytokine ciliary neurotrophic factor (CNTF) can provide potent neuroprotection for photoreceptors in various retinal degeneration models and has thus been tested in clinical trials aimed at treating blinding diseases." (PMID 40671803, 2025). "This includes ciliary neurotrophic factor (CNTF) using encapsulated cells implanted intravitreally to treat retinal degeneration." (PMID 37626902, 2023). "Recent results from a phase 2 clinical trial concluded that a surgical implant sutured to the pars plana that delivers ciliary neurotrophic factor (CNTF) via an encapsulated cell technology (ECT) slowed the progression of retinal degeneration in MacTel2." (PMID 37968753, 2023). "Ciliary neurotrophic factor (CNTF) is a member of the interleukin (IL)-6 family of neuropoietic cytokines that has been noted to protect photoreceptors during retinal degeneration in animal models." (PMID 35890368, 2022). "Ciliary neurotrophic factor (CNTF) acts as a potent neuroprotective cytokine in multiple models of retinal degeneration." (PMID 36396639, 2022). "Despite the promise of CNTF as a broad-spectrum neuroprotective agent to attenuate retinal degeneration, we and others have observed that prolonged exposure to high levels of CNTF can be detrimental to visual function in animal models of RD14–17." (PMID 32313077, 2020). "Together, results of these molecular analyses demonstrate the impacts of CNTF treatments on the retinal transcriptome in diseased conditions, thus providing valuable insight for CNTF clinical trials aimed at attenuating retinal degeneration in patients." (PMID 32313077, 2020). "Numerous studies have suggested that CNTF and the activation of IL-6 signaling, also through overexpression of STAT3, are important in the response to retinal degeneration although treatment with CNTF has shown limited efficacy in RP patients." (PMID 33071752, 2020). "Ciliary neurotrophic factor (CNTF) was the first neuroprotective agent to progress to clinical trials, based on extensive preclinical evidence for slowing retinal degeneration in animal models." (PMID 32668775, 2020). "Ciliary neurotrophic factor (CNTF) has been tested in clinical trials for human retinal degeneration due to its potent neuroprotective effects in various animal models." (PMID 32313077, 2020). "GFs such as neural growth factor (NGF), brain-derived neurotrophic factor (BDNF) and ciliary neurotrophic factor (CNTF) can significantly slow retinal degeneration and stop the progression in clinical and preclinical trials." (PMID 31931872, 2020). "It has been reported that the phosphorylation of signal transducer and activator of transcription 3 (STAT3) and ERK in Müller cells plays an important role in ciliary neurotrophic factor (CNTF)-mediated photoreceptor rescue in the retinal degeneration." (PMID 31179317, 2019). "High IL-6 and decreased CNTF levels have been shown to contribute to retinal degeneration and neurodegeneration in DR." (PMID 32116675, 2019).
retinal degeneration (continued). "CNTF can enhance photoreceptor survival, as demonstrated in multiple animal models of retinal degeneration, ranging from zebrafish to canine models." (PMID 29795129, 2018). "Ciliary neurotrophic factor (CNTF) delays photoreceptor degeneration in human retinal degeneration and animal models such as rd1 and Q334ter mice." (PMID 27893855, 2016). "In fact, the intravitreal injection of CNTF in a feline model of hereditary retinal degeneration leads to the long-term survival of photoreceptors." (PMID 24672707, 2014). "A major role of CNTF in mediating the neuroprotective effects of lens injury on photoreceptors is also supported by previous reports, demonstrating that CNTF is neuroprotective to photoreceptors in different animal models of retinal degeneration." (PMID 24558606, 2013). "This inference is supported by the finding that CNTF is upregulated in response to retinal degeneration and injury that results in Müller cell gliosis." (PMID 21637858, 2011). "We found that several genes that are induced by CNTF in quiescent Müller cells are also upregulated in gliotic Müller cells from inherited and experimentally-induced retinal degenerations." (PMID 21637858, 2011). "Among them, (CNTF ciliary neurotrophic factor) has shown a promising capability to inhibit progression of retinal degenerations in a variety of animal models, as well as in light-induced damage." (PMID 20209167, 2010). "Consistent with this notion is a recent finding in a Phase I clinical trial using CNTF for retinal degenerations, in which one patient with late-stage RP had a significant improvement of vision." (PMID 20209167, 2010). "Moreover, a combination of GDNF and CNTF was reported to afford higher protection to photoreceptors in a retinal degeneration (rd) mouse." (PMID 34803580, 2021). "Interestingly, many genes induced by CNTF were also highly expressed in reactive Müller cells from mice with inherited or experimentally induced retinal degeneration." (PMID 21637858, 2011). "Furthermore, CNTF is capable of retarding retinal degeneration in several animal models of retinitis pigmentosa." (PMID 21637858, 2011). "CNTF acts as a neuroprotective agent in many animal models of retinal degeneration." (PMID 21637858, 2011). "Long-term treatment with CNTF starting at early stages of degeneration could be a viable strategy for preservation of central vision for patients with retinal degenerations." (PMID 20209167, 2010). "The isolation of Crx, and Caspase-3 as downregulated genes is consistent with CNTF-inhibited photoreceptor differentiation as well as the neuroprotective effect of CNTF on different models of retinal degeneration and therefore demonstrates the quality of the DC6 subtraction." (PMID 17327826, 2007). "One such factor is ciliary neurotrophic factor (CNTF), where non-viral delivery alleviated photoreceptor loss in the rd1, nervous (nr/nr) and RhoQ344ter mouse models of retinal degeneration, Rdy feline model of retinal atrophy, and rcd1 canine model of retinitis pigmentosa (RP)." (PMID 36710928, 2022). "CNTF demonstrated potent neurotrophic activities in vitro and in animal models of neurodegenerative diseases, leading to clinical trials in patients suffering from Huntington’s disease, amyotrophic lateral sclerosis and promising effects in retinal degeneration pathologies." (PMID 29507344, 2018). "Moreover, CNTF is upregulated in response to retinal degeneration and injury." (PMID 21637858, 2011). "When modified with SH3 binding peptides, there was a stable release of ciliary neurotrophic factor (CNTF) with successful delivery in mouse retina, leading to downregulated phototransduction genes in retinal degeneration." (PMID 38203940, 2023).
retinal degeneration (continued). "For example, ciliary neurotrophic factor (CNTF), the best studied neurotrophic factor for retinal degenerations, has been investigated for a variety of neural degenerative diseases in the retina, including RP, macular degeneration, and macular telangiectasia." (PMID 29687079, 2018). "Although CNTF and PEDF have been shown to rescue photoreceptor morphologies and prolong photoreceptor survival in rodent models of retinal degeneration, they may suppress retinal function, as determined by ERG recoding." (PMID 37077319, 2023). "For example, ciliary neurotrophic factor (CNTF) was shown to be effective in protecting photoreceptors in mouse, dog, and chicken models of retinal degeneration." (PMID 34184634, 2021). "As the retinal degeneration starts, the activated microglia invade the degenerated photoreceptor layer and reduce the expressions of neurotrophic factors including nerve growth factor (NGF), ciliary neurotrophic factor (CNTF), and glial cell line-derived neurotrophic factor (GDNF)." (PMID 37728589, 2024).
glaucoma (27 papers, 2013 to 2026). Increased pressure in the eyeball due to obstruction of the outflow of aqueous humor. "Along with other strategies such as nicotinamide, recombinant human nerve growth factor, ciliary neurotrophic factor, and anticomplement C1q antibody, topical insulin has a strong scientific premise as a therapeutic for glaucoma." (PMID 41584099, 2026). "Ciliary neurotrophic factor (CNTF) expression is altered in ganglion cells after glaucoma induction and had a neuroprotective effect in glaucoma models of rat retinas." (PMID 37240082, 2023). "Müller cells, a macroglia cell type, protect RGCs from glaucoma‐induced damage by secreting neurotrophic factors (ciliary neurotrophic factor (CNTF)) and antioxidants (glutathione and ghrelin)." (PMID 36924268, 2023). "In an ocular hypertension-induced rat model of glaucoma, the administration of CNTF resulted in substantial reduction of the RGC loss, suggesting that CNTF promotes the survival of RGCs." (PMID 35668928, 2022). "The findings of this study have important implications for using CNTF and astrocytes as therapeutic agents for neurodegenerative diseases, such as glaucoma." (PMID 35925584, 2022). "Future investigations examining retinal cell type-specific effects of CNTF will facilitate elucidating cellular mechanisms for the ongoing CNTF glaucoma trials." (PMID 36396639, 2022). "CNTF is expressed in all layers of the retina, the retinal pigment epithelium, and the optic nerve head, though its expression is decreased in glaucoma patients." (PMID 34200991, 2021). "For example, the cytokines and neurotrophic factors secreted from MSCs, such as brain neurotrophic factor, ciliary neurotrophic factor, and basic fibroblast growth factor, have been shown to provide neuroprotective effects in experimental models of glaucoma." (PMID 34733333, 2021). "The neurotrophic properties of CNTF were tested in several animal models of glaucoma and in ischemic optic neuropathy." (PMID 32218163, 2020). "Several NTFs have been reported to be associated with glaucoma, including nerve growth factor (NGF), brain-derived neurotrophic factor (BDNF), ciliary neurotrophic factor (CNTF), fibroblast growth factor 2 (bFGF), glial-derived neurotrophic factor (GDNF), and neurturin." (PMID 36579616, 2022). "In addition, Müller cells secrete neurotrophic factors, such as ciliary neurotrophic factor (CNTF), and the antioxidants glutathione and ghrelin, protecting RGCs from damage in glaucoma." (PMID 34121982, 2021). "CNTF protects RGCs in experimental models of glaucoma and ischemic optic neuropathy." (PMID 34200991, 2021). "Notably, the concentration of CNTF in the aqueous humor, lacrimal fluid and blood serum is decreased in patients with glaucoma." (PMID 32218163, 2020). "In addition, virally mediated overexpression of CNTF has also been reported to exert neuroprotective effects in experimental glaucoma models." (PMID 27657046, 2016). "The intravitreal injection of CNTF in rat glaucoma models improved the survival rate of RGCs." (PMID 24066234, 2013). "Finally, the ciliary neurotrophic factor (CNTF), participating in oxygen consumption regulation, has been proposed as a glaucoma biomarker, since lower levels of CNTF were found in the tear film and aqueous humor of patients with POAG (n = 55) compared to control subjects (n = 61)." (PMID 34439995, 2021). "Neurotrophic factors such as nerve growth factor (NGF), BDNF, CNTF, FGF-2, glial cell-line-derived neurotrophic factor (GDNF), neurturin (NRTN), and neuritin are particularly relevant to glaucoma." (PMID 39458902, 2024). "In a glaucoma model and after ischemia/reperfusion of the retina, MSC increase RGC survival and the expression of CNTF and FGF-2 in the retina." (PMID 25347773, 2014). "Thus, neurotrophic supplementation therapies, such as nerve growth factor (NGF), brain-derived neurotrophic factor (BDNF), or ciliary neurotrophic factor (CNTF), have been studied for preventing the progression of glaucoma." (PMID 39408817, 2024).
glaucoma (continued). "Because optic neuropathies such as glaucoma are slowly progressing neurodegenerative disorders, we next analysed whether the synergistic rescue effect of GDNF and CNTF is long-lasting." (PMID 34827174, 2021). "Thus, while CNTF may provide protection for retinal ganglion cells in glaucoma, it may not be suitable for photoreceptor protection in retinitis pigmentosa." (PMID 39408817, 2024).